GSK3B (glycogen synthase kinase 3 beta)
Diseases named in the same sentence as GSK3B in open-access papers (continued):
Sharing a sentence is not in itself a finding about the gene and the disease.
melanoma (continued). "To confirm GSK3β upregulation and its activation also on the protein level, we employed Western blot analysis with cell lysates from BRAF-V600E melanoma cells before, during BRAFi treatment and once resistance has developed." (PMID 40184329, 2025). "GSK3β expression and activation in A375 BRAF-V600E mutant melanoma cells were assessed prior to BRAFi treatment, in BRAFi-sensitive cells and after developing BRAFi resistance at RNA and protein levels." (PMID 40184329, 2025). "Western blot analysis showed that EUE treatment under 1.5 mM H2O2 stress increased the expression of MITF, TYR, β-catenin, GSK-3β, p-GSK-3β, and Wnt-5a in B16 melanoma cells." (PMID 41496855, 2025). "Fourteen overlapping targets (GSK3B, MAPK1, HSPA8, VEGFA, FGF2, MTOR, and so on) were considered potential targets for the treatment of melanoma with salidroside." (PMID 40708947, 2025). "Rifampicin demonstrated robust anti-melanogenic effects in B16F10 melanoma cells by targeting multiple signaling pathways involved in melanogenesis, including cAMP/PKA, MAPK, and GSK-3β/β-catenin pathways." (PMID 40005210, 2025). "We found that E-cadherin and GSK-3β were up-regulated while vimentin and β-catenin were downregulated in si-LINC00662 melanoma cells." (PMID 38169586, 2024). "As further evidence that components of the GSK3β/MITF axis are affected by Rab7a/TPC2 activity, we demonstrated that β-Catenin is reduced in Rab7a as well as in TPC2 KO melanoma lines." (PMID 39562548, 2024). "RA possesses an inhibitory effect on melanoma cells’ proliferation, movement, and invasion via inhibiting expression of the ADAM17/EGFR/AKT/GSK3β axis." (PMID 36247004, 2022). "Unexpectedly, melatonin was found to modulate the PI3K/AKT pathway, suppressing AKT phosphorylation to activate GSK-3β in SK-MEL-1 and MEL-HO melanoma cells." (PMID 35897696, 2022). "In another study, anticancer effects of RA in A375 cells melanoma cells via downregulation of ADAM17 and expression of ADAM17/EGFR/AKT/GSK3β were also evaluated." (PMID 36247004, 2022). "We further showed that eEF2K promotes stabilization of PD-L1 protein through its interaction with GSK3β, and that knockdown of eEF2K decreased PD-L1 expression and increased CD8+ T cell number and granzyme B (GZMB) in tumor tissues in a mouse melanoma model." (PMID 35347072, 2022). "The human melanoma A375 cells were exposed to RA, then cell viability, migration, invasion, apoptosis, melanin content and the expression of ADAM17/EGFR/AKT/GSK3β were evaluated." (PMID 34224305, 2021). "Our findings verified that ABZ treatment suppresses the EMT of melanoma in vitro and in vivo by inhibiting the AKT/GSK-3β pathway, resulting in decreased pGSK-3β/Ser9 (inactive form of GSK-3β) expression." (PMID 34966427, 2021). "Together, the results suggest that melatonin modulates the PI3K/AKT pathway and activates GSK-3β in both SK-MEL-1 and MEL-HO melanoma cells." (PMID 32674468, 2020). "SNX-2112 induced a time-dependent degradation of HSP90 client proteins crucial for melanoma cell maintenance including AKT, IKKα, BRAF and glycogen synthase kinase 3 beta (GSK-3β)." (PMID 31659567, 2020). "Further, the genes upregulated upon Rec KD in A375 cells included factors such as WNT5B and GSK3B, which are known to induce the EMT-like process and are activated when melanoma gets relapsed to metastasis after failed treatment." (PMID 33202765, 2020). "As ex-vivo proof of concept of the therapeutic modulation of GKS3β in the melanoma TME, single-cell suspensions from melanoma metastases (n=4) were transduced with CA.GSK3β." (PMID 30400822, 2018). "Since inhibition of GSK3β in melanoma cells leads to cellular changes paralleling PAX3 inhibition, it was claimed that GSK3β regulates proliferation and morphology of melanoma cells through phosphorylation of PAX3." (PMID 27906130, 2016).
melanoma (continued). "Similarly, miglitol, an oral antidiabetic drug, demonstrated melanin synthesis inhibition in B16F10 melanoma cells by regulating PKA, MAPK, and GSK-3β/β-catenin signaling pathways, making it a promising ingredient for skin-whitening products." (PMID 40005210, 2025). "Nevertheless, its involvement in melanoma and its effects on the GSK3β signaling pathway have not been fully elucidated." (PMID 41153674, 2025). "BRAFi-resistant melanoma cells displayed increased GSK3β expression as opposed to BRAFi-sensitive cells." (PMID 40184329, 2025). "Western blot analyses of both in vivo and in vitro revealed that IR-546 induces apoptosis and inhibits metastasis of melanoma by activating the mitochondrial apoptosis pathway, suppressing the AKT/GSK3β signaling pathway, and downregulating the β-catenin signaling pathway and its downstream targets." (PMID 40495167, 2025). "Specifically, Wnt/β-catenin signaling pathway related genes such as β-catenin, GSK3β, Anxin, and DVL are pivotal to melanocyte development and pathogenesis of melanoma, directing neural crest cell differentiation to form melanocytes and driving melanoma cell proliferation and invasion." (PMID 38167452, 2024). "E-cadherin and GSK-3β were up-regulated whereas vimentin and β-catenin were downregulated in si-LINC00662 melanoma cells, and si-LINC00662 can also reduce the levels of β-catenin protein in the nucleus which might affect β-catenin transcriptional activity." (PMID 38169586, 2024). "Thus, the melanin production mediated by the compound CC7 was probably triggered through Akt/GSK-3β/β-catenin pathways, which is consistent with reports revealing that the activation of GSK3/β-catenin influenced melanin production in B16 melanoma cells." (PMID 36902210, 2023). "Interestingly, a recent study showed that the inhibition of glycogen synthase kinase-3 beta (GSK3β) decreases the expression of PD-1 on CD8+ T cells and is as effective as anti-PD-1/anti-PD-L1 antibodies for controlling B16F10 melanoma." (PMID 34649584, 2021). "CCR5 is involved in proliferation and migration of melanoma cells in vitro and supports the mesenchymal phenotype of metastatic melanoma cells by increasing TGF-β1, which in turn induces EMT and migration via PI3K/AKT/GSK3β signaling." (PMID 32630699, 2020). "It was revealed that CoQ0, a major active constituent of antrodia camphorata, inhibited the migration and invasion of melanoma cells via down-regulating Wnt/β-catenin mainly owing to the increasing of Axin rather than GSK3β." (PMID 31555129, 2019). "The selective GSK-3α and GSK-3β inhibitor LY2090314 shows very high cytotoxic activity in melanoma cells, both resistant and nonresistant to BRAF inhibitor." (PMID 29379583, 2017). "At variance, GSK3A, but not GSK3B, has been identified as a therapeutic target in melanoma suggesting that, similarly to what has been reported for normal cells, the two isoforms can play both distinct or redundant roles depending on the cancer cell type." (PMID 24984063, 2014). "We also demonstrated that vimentin expression was sufficient to induce increased mesenchymal/pro-metastasic phenotypic changes in melanoma cells, including ILK/GSK3-β-dependent E-cadherin down-regulation, Snail1 activation and increased cell motility and migration." (PMID 23785295, 2013). "From studies on epithelial cells, carcinomas, gliomas and melanomas, it appears that Smads, through their linker domain, are at the point of convergence of major cellular signaling pathways, involving ERK, JNK, p38, CDK, GSK3β." (PMID 23077590, 2012). "We specifically analyzed the effects of CA treatment on factors such as cell viability, cell cycle progression, apoptosis induction, and the modulation of p-GSK3β expression in melanoma cell lines, aiming to determine the potential of CA as a novel therapeutic strategy for melanoma." (PMID 41153674, 2025).
melanoma (continued). "Based on our data, including data confirming reduced endolysosomal function in Rab7a as well as TPC2 KO SK-MEL-5 melanoma cells for other cells, we postulate that activation of TPC2, enhanced by Rab7a promotes endolysosomal activity and thus degradation of GSK3β." (PMID 39562548, 2024). "It was suggested that targeting Axin1 stability by post-translational modifications like phosphorylation by GSK-3β, PARsylation by tankyrase-1/2 (TNKS1/2), methylation by protein arginine methyltransferase 1 (PRMT1), and SUMOylation could sensitize melanoma cells to TRAIL-based therapies." (PMID 34577571, 2021). "TPC2 inhibition thus provides a twofold benefit in melanoma prevention and treatment by increasing, through interference with tyrosinase activity, the synthesis of UV blocking melanin in melanosomes and by decreasing MITF-driven melanoma progression by increased GSK3β-mediated MITF degradation." (PMID 33875769, 2021). "Furthermore, it was proven that activation of Wnt/β-catenin pathway could increase the levels of p-GSK3β (Ser9), MYC and Cyr61, while MYC overexpression elevated the levels of MYC and Cyr61 in melanoma cells with circ-GLI1 silence." (PMID 32732916, 2020). "Recently, our research team revealed that fisetin binds to GSK-3β at non-ATP-binding site—through molecular docking prediction—and consequently activates β-catenin in B16F10 melanoma cells." (PMID 33863923, 2021). "Interestingly, previous studies in HeLa cells have shown that inhibition of GSK3A, but not GSK3B, enhanced sensitivity to TRAIL-mediated apoptosis, raising the possibility that some of the effects of CHIR99021 in our melanoma cells may be mediated through GSK3A." (PMID 23869245, 2013).
cardiac hypertrophy (117 papers, 2008 to 2025). "Studies have found that Endog deficiency can promote cardiac hypertrophy through reactive oxygen species (ROS) accumulation, activation of the Akt and GSK3β signalling pathways, and HDAC4 and HDAC5 nuclear export." (PMID 40497340, 2025). "Extensive research has demonstrated that inhibiting the AKT/GSK3β signaling pathway can reduce pathological cardiac hypertrophy caused by pressure overload." (PMID 39937832, 2025). "To further validate the role of the YAP1/AKT/GSK3β signaling in cardiac hypertrophy, we employed H9c2 cells to elucidate the underlying mechanisms." (PMID 39937832, 2025). "In cardiac pathology, GSK3α enhances cardiomyocyte proliferation and ameliorates heart failure, while GSK3β is associated with cardiac hypertrophy and fibrosis." (PMID 41300341, 2025). "It has been suggested that GSK3β is an endogenous negative regulator of cardiac hypertrophy, the activity of which is strictly controlled by its phosphorylation, and inhibition of Ser9 phosphorylation in GSK3β reduces cardiac hypertrophy and risk of HF." (PMID 35855640, 2023). "Because of its phosphorylatio, inhibition of GSK3β is associated with cardiac hypertrophy in response to endothelin-1 or phenylephrine." (PMID 33240671, 2020). "GSK3β has been implicated in cardiomyocyte proliferation during embryonic development of the heart, in post myocardial infarction remodeling and in cardiac hypertrophy." (PMID 30978208, 2019). "Nuclear factor of activated T-cells (NFAT) is associated with the promotion of cardiac hypertrophy, glycogen synthase kinase-3β (GSK-3β) is considered to function as a negative regulator, mainly by modulating NFAT activity." (PMID 27977752, 2016). "By knockout Dvl-1 gene, ANF and BNP expression decreased, AKT activity was inhibited, but GSK-3β activity was activated, which relieved cardiac hypertrophy caused by overload pressure." (PMID 26282432, 2015). "During the development of cardiac hypertrophy, Akt is activated and causes the phosphorylation and inactivation of the antihypertrophic kinase GSK-3β." (PMID 24971153, 2014). "Additionally, the involvement of GSK-3β in the development of cardiac hypertrophy is linked with its activation, and that, in turn diminished hypertrophy in response to chronic beta-adrenergic stimulation and pressure overload." (PMID 37626874, 2023). "Then, the inactive GSK3β could promote β-catenin to enter the nucleus and cause cardiac hypertrophy." (PMID 36834623, 2023). "Given that exposed offspring exhibited postnatal catch-up growth, which can be associated with increased risk of developing cardiovascular disease and remodelling, we next sought to elucidate the underlying molecular changes previously associated with cardiac hypertrophy (e.g., GSK-3β)." (PMID 33879850, 2021). "In addition, we revealed that the protective role of RFP on the development of cardiac hypertrophy is associated with the inhibition of the canonical Wnt/GSK-3β/β-catenin signalling pathway." (PMID 29423029, 2018). "Relevant studies have demonstrated that Gsk‐3β plays an important role in several cardiovascular diseases, including cardiac hypertrophy and heart failure." (PMID 40753540, 2025). "GSK‐3β mediates the cardiac hypertrophy‐protective effects of a low‐carbohydrate diet, and its activation is also involved in the anti‐hypertrophic effects of quercetin." (PMID 40753540, 2025). "Several miRNAs, miRNA-21, miRNA-199a, miRNA-26, miRNA-378, and miRNA-29c have been shown to regulate the development of pathological cardiac hypertrophy by targeting GSK3β." (PMID 40771283, 2025). "Gsk‐3β, a negative regulator of cardiac hypertrophy and a downstream target of Akt, is inhibited through Akt‐mediated phosphorylation." (PMID 40753540, 2025). "mTOR and Gsk‐3β, as downstream molecules of Akt, are involved in mediating pathological cardiac hypertrophy." (PMID 40753540, 2025).
cardiac hypertrophy (continued). "In conclusion, we demonstrate that MARCH5 promotes cardiac hypertrophy through the Akt/mTOR/Gsk‐3β/GATA4 pathway." (PMID 40753540, 2025). "Our study identifies MARCH5 as a novel regulatory component in myocardial hypertrophy through its modulation of the Akt/mTOR/Gsk‐3β/GATA4 signalling axis." (PMID 40753540, 2025). "Activated glycogen synthase kinase 3 beta (GSK-3β) inhibits heart hypertrophy in response to pressure overload and adrenergic stimulation." (PMID 39482911, 2025). "Our findings suggest that MARCH5 participates in the pathological cardiac hypertrophy by regulating the Akt/mTOR/Gsk‐3β/GATA4 pathway, positioning it as a promising therapeutic target for cardiac hypertrophy." (PMID 40753540, 2025). "Mechanistically, both in vivo and in vitro experiments demonstrated that overexpression of LIMD1 significantly inhibits the activation of the YAP1/AKT/GSK3β signaling pathway, thereby reversing pathological cardiac hypertrophy induced by pressure overload." (PMID 39937832, 2025). "Some studies suggested that GSK3β acts as a negative regulator of cardiac hypertrophy and is inactivated in patients with heart failure." (PMID 38732116, 2024). "The Akt-GSK3β/mTOR signaling pathway is deeply involved in the progress of cardiac hypertrophy and remodeling." (PMID 38481817, 2024). "Treatment with the GSK-3β inhibitor TDCD-8 reversed the inhibitory effect on cardiac hypertrophy in these mice." (PMID 39451203, 2024). "To investigate how the inhibition of GSK-3β phosphorylation by O-GlcNAcylation affects cardiac hypertrophy and function in vivo, we injected TDZD-8, in Ogt-Tg mice before TAC." (PMID 37033243, 2023). "On the contrary, when NFAT is phosphorylated by glycogen synthase kinase-3β (GSK-3β), this makes it translocate from the nucleus to the cytosol and the signaling pathways of cardiac hypertrophy are inhibited." (PMID 37033243, 2023). "Collectively, the activation of GSK-3β by O-GlcNAcylation prevents pressure overload and Ang II-induced cardiac hypertrophy by inhibiting the NFAT signaling pathway." (PMID 37033243, 2023). "GSK-3β induces cardiac hypertrophy through the promotion of NFAT nuclear translocation; therefore, we confirmed that the TDZD-8 treatment induced the nuclear translocation of NFAT in Ang II-stimulated H9c2 cells." (PMID 37033243, 2023). "GSK-3β shows high activity in the basal condition (i.e., unstimulated cells) and inhibits various pathways that promote cardiac hypertrophy (for example, GSK-3β phosphorylates the nuclear factor of activated T-cells and induces its nuclear export)." (PMID 37469482, 2023). "Phosphorylated NFAT by GSK-3β is retained in the cytoplasm and cannot induce cardiac hypertrophy, indicating that the phosphorylation state of GSK-3β is important for the NFAT signaling pathway." (PMID 37033243, 2023). "It has also been reported that the inactivation of GSK-3β with lithium promotes pressure overload-induced cardiac hypertrophy in rats via β-catenin." (PMID 37033243, 2023). "As expected, the inhibitory effects of Trim44 KO on pathological cardiac hypertrophy induced by ISO treatment were exerted by suppressing the AKT/mTOR/GSK3β/P70S6K signaling pathway." (PMID 35855640, 2023). "Transgenic mice overexpressing a constitutively active form of GSK-3β were shown to reduce the cardiac hypertrophy induced by the activation of calcineurin, β-adrenergic stimulation, and pressure overload." (PMID 37033243, 2023). "Studies have reported that the Akt/GSK3β and p38 signaling pathways participate in cardiac hypertrophy." (PMID 36834623, 2023). "They stated that endurance training decreased GSK3β and thus increased mTOR levels, which is an important factor in cardiac hypertrophy." (PMID 37274326, 2023). "Antioxidant effect (inhibit MAPK/mitochondria‐dependent apoptotic pathway); reduces myocardial hypertrophy (activation of Akt/GSK‐3β‐mir‐126‐mediated signaling pathway)." (PMID 37324906, 2023).